IRAK1 (interleukin 1 receptor associated kinase 1)
Diseases named in the same sentence as IRAK1 in open-access papers (continued):
Sharing a sentence is not in itself a finding about the gene and the disease.
leukemia (9 papers, 2014 to 2025). A malignant (clonal) hematologic disorder, involving hematopoietic stem cells and characterized by the presence of primitive or atypical myeloid or lymphoid cells in the bone marrow and the blood. "miR-146b-5p has previously been implicated in leukemia development and targets genes such as IRAK1, which has been implicated in a wide variety of cancer phenotypes as well as influencing the immune response." (PMID 34906138, 2021). "Our next question was why IRAK1-expressing, mock control leukemia cells survived and cause disease in hosts with a competent immune system." (PMID 34906138, 2021). "The IRAK1 KO in the leukemia cells is very specific and highly efficient in depleting the target gene specifically in the leukemia cells, while IRAK1 inhibitor treatment has relatively low efficiency, due to the method of delivery." (PMID 34906138, 2021). "Given that CD4+ helper T cells are also involved in eradication of IRAK1 KO leukemia cells, we also analysed the ability of MDSC to suppress CD4+ T cells." (PMID 34906138, 2021). "Together, these experiments demonstrate that loss of IRAK1 expression in the tumor cells leads to immunity related tumor clearance where both the activated CD4+ and CD8+ T-cells are directly responsible for suppressing leukemia development." (PMID 34906138, 2021). "It seems, therefore, that IRAK1 may more specifically affect leukemia progression through a mechanism distinct from cell proliferation/viability." (PMID 34906138, 2021). "We now show that FGFR1 fusion kinase-mediated activation of IRAK1 in SCLL cells leads to increased accumulation of myeloid-derived suppressor cells (MDSCs) in vivo with a concomitant suppression of CD4/CD8 T-cells promoting an immune suppressive microenvironment leading to leukemia development." (PMID 34906138, 2021). "Since the observation indicates that CD4+ and CD8+ cells are responsible for the rejection of IRAK1 KO SCLL cells in syngeneic hosts, we investigated the status of these T cells in these leukemia free mice." (PMID 34906138, 2021). "To further examine the activation of CD4+ T-cells in the IRAK1 null leukemia model, we performed CD4 cell polarization analysis with splenocytes isolated from IRAK1 KO cell-engrafted, tumor free mice." (PMID 34906138, 2021). "Recent papers have given evidence that rs2910164 in miR146 can modify the expression of nuclear factor (NF-ĸB) through reducing IRAK1 and TRAF gene expression thus, driving inflammation and leukemia progression in myeloid cells." (PMID 34804964, 2021). "When IRAK1 KO#7 cells were inoculated into the four different groups of mice, disease did not develop in isotype treated mice but leukemia developed in mice that were depleted either individually for CD4 or CD8 or combined CD4/CD8 cells." (PMID 34906138, 2021). "To determine whether IRAK1 has a broader influence on different leukemia subtypes, we used CRISPR/Cas9 to knock out IRAK1 in ZMYM2-FGFR1 expressing ZNF112 cells, which predominantly show a T-cell ALL immunophenotype." (PMID 34906138, 2021). "Inhibition of IRAK4 and IRAK1, either with short hairpin RNA (shRNA) or with an IRAK1/4dual inhibitor, resulted in decreased expression of IL-17 and interferon-γ (IFN-γ), as well as reduced progression of T-ALL proliferation in a murine leukemia model." (PMID 27845762, 2016). "However, current research on IRAK1/4 inhibitors mainly targets non-solid tumors, such as leukemia, suggesting that not all solid tumors are amenable to this treatment." (PMID 40083694, 2025). "Because IRAK1 KO cells generate leukemia in immune-deficient NSG mice but not in immune-competent syngeneic hosts, the immune system was implicated in playing a critical role in eradication of the IRAK1 KO cells." (PMID 34906138, 2021).
leukemia (continued). "IRAK1 orchestrates a previously unknown FGFR1-directed immune escape mechanism in SCLL, through induction of MDSCs via regulation of IFN-γ signaling from leukemia cells, and targeting IRAK1 may provide a means of suppressing tumor growth in this syndrome by restoring immune surveillance." (PMID 34906138, 2021).
pancreatic cancer (9 papers, 2012 to 2025). "Then, targeting IRAK1/4 could be a potential therapeutic strategy to suppress enhancive tumorigenesis in BAP1 deficient pancreatic cancer." (PMID 40083694, 2025). "Thus, we were interested in investigating the anti-tumoral effect of a dual IRAK1/4 inhibitor (named IRAK1/4i) in BAP1 deficient pancreatic cancer models." (PMID 40083694, 2025). "Our findings above indicated that BAP1 deficient pancreatic cancer might be sensitive to the targeted inhibition of IRAK1/4." (PMID 40083694, 2025). "DIM also induced the expression of miR-146a, which resulted in reduced pancreatic cancer cell invasion via inhibition of metastasis-associated protein 2 (MTA-2), interleukin-1 receptor-associated kinase 1 (IRAK-1), and NFκB." (PMID 25853141, 2015). "In both pancreatic cancer and gastric cancer cells, EGFR and the NF-κB regulatory kinase interleukin 1 receptor-associated kinase 1 (IRAK-1) were proven to be.miR-146a target genes." (PMID 23555954, 2013). "In pancreatic cancer cells, miR-146a inhibits the invasive capacity with concomitant down-regulation of EGFR and the NF-kappaB regulatory kinase, interleukin 1 receptor-associated kinase 1 (IRAK-1)." (PMID 22681957, 2012). "Treatment of pancreatic cancer cells with isoflavone compounds (including 70.54% genistein), increased miR-146a expression, causing downregulation of EGFR, MTA-2, IRAK-1, and NF-κB, resulted in inhibition of cell invasion." (PMID 22928040, 2012). "Interestingly, 50% inhibitory concentration (IC50) assessment indicated that BAP1 deletion sensitized pancreatic cancer cells to the treatment of IRAK1/4i." (PMID 40083694, 2025). "Treatment with DIM (which increased miR-146a expression) or reexpression of miR-146a downregulated EGFR, interleukin 1 receptor-associated kinase 1 (IRAK-1), NF-κB and metastasis-associated protein, member 2 (MTA2), blocking cell invasion in Colo357 and Panc-1 pancreatic cancer cells." (PMID 25254214, 2014). "EGFR has been reported as a target of miR-146a in cancer, and miR-146a can block pancreatic cancer cell invasion and metastasis by inhibiting EGFR and IRAK1." (PMID 33985523, 2021).
glioma (8 papers, 2022 to 2024). A benign or malignant brain and spinal cord tumor that arises from glial cells (astrocytes, oligodendrocytes, ependymal cells). "Our findings demonstrate the HNRNPC–IRAK1–MAPK axis as a crucial carcinogenic factor for glioma and the novel underlying mechanism of IRAK1 upregulation, which provides a rationale for therapeutically targeting epitranscriptomic modulators in glioma." (PMID 38830885, 2024). "Recent data showed that IRAK1 is highly expressed in gliomas and is associated with radiotherapy sensitivity." (PMID 38830885, 2024). "The glioma public datasets and tissue microarrays (TMAs) data indicated that IRAK1 overexpression was associated with poor prognosis, and IRAK1 knockdown significantly repressed malignant biological behavior in vitro." (PMID 38830885, 2024). "Remarkably, an increasing number of foci were detected at 24 h post IR in IRAK1 silencing glioma cells, indicating persistent DNA damage caused by IRAK1 knockdown." (PMID 37031183, 2023). "Firstly, we transfected PRDX1 overexpression plasmid into IRAK1-deficient glioma cells, which was verified by Western blotting." (PMID 37031183, 2023). "We demonstrated that HNRNPC facilitates glioma progression and helps maintain the mRNA stability of interleukin-1 receptor-associated kinase 1 (IRAK1) in an m6A-dependent manner, resulting in activation of the mitogen-activated protein kinase (MAPK) signaling pathway." (PMID 38830885, 2024). "The result verified that IRAK1 expression level has a significantly positive association with tumor recurrence (p = 0.001) and higher pathological grade (p = 0.037), suggesting that IRAK1 might play a tumor-promoting role in glioma." (PMID 37031183, 2023). "As shown by our analysis of the information from the TCGA and CGGA databases, IRAK1 expression in glioma tissues was significantly higher than that in normal brain tissues and IRAK1 expression was positively correlated with the degree of malignancy in gliomas." (PMID 38830885, 2024). "The introduction of a miR-146a-5p mimic led to the downregulation of IRAK1 in glioma cells, which in turn significantly reduced their invasive potential." (PMID 39451208, 2024). "We demonstrated the role of HNRNPC in tumorigenesis and its function in regulating IRAK1 mRNA stability in an m6A-dependent manner, which was necessary for the malignant behavior of glioma cells by resulting in activation of the MAPK signaling pathway." (PMID 38830885, 2024). "The protein level of IRAK1 was decreased in HNRNPC-knockdown glioma cells, whereas IRAK1 protein was increased after overexpressing HNRNPC." (PMID 38830885, 2024). "We then examined IRAK1 protein expression in glioma tissues using two TMAs and found that IRAK1 protein expression was significantly upregulated in glioma tissues and positively correlated with the tumor grade." (PMID 38830885, 2024). "Quantitative scoring of the TMA HBraG155Su01 results via IHC further demonstrated that IRAK1 expression positively correlated with HNRNPC expression in glioma tissues." (PMID 38830885, 2024). "Based on our findings, it is reasonable to conclude that IR-induced IRAK1 overexpression markedly attenuating the autophagic cell death stimulated by IR contributes to the development of secondary radioresistance in glioma." (PMID 37031183, 2023). "The Kaplan-Meier survival analysis from TCGA and Rembrandt datasets, showing a worse prognosis of glioma patients with higher IRAK1 expression, further indicated the correlation of IRAK1 in glioma development." (PMID 37031183, 2023). "In this manuscript, we found that IRAK1 expression is elevated in glioma patients from our department, TCGA, and Rembrandt cohorts." (PMID 37031183, 2023). "To gain a deeper insight into the biological function of IRAK1 in glioma, we detected the endogenous expression of IRAK1 in four human established glioma cell lines and NHA cells." (PMID 37031183, 2023).
glioma (continued). "Western blotting and qRT-PCR analyses showed that the protein and transcript levels of IRAK1 were obviously higher in all four glioma cell lines compared to NHA cells." (PMID 37031183, 2023). "We used TRAF6 and IRAK1 as a gene set and evaluated its effect on the survival time of glioma patients in TCGA." (PMID 37391426, 2023). "Subsequently, we observed that IRAK1 knockdown markedly impedes glioma cell proliferation, migration, and invasion in vitro." (PMID 37031183, 2023). "Following the transfection of sh-IRAK1 or sh- negative control (NC) lentivirus, the efficiency was verified with Western blotting and qRT-PCR assays, suggesting the successful construction of stable IRAK1-knockdown glioma cell models." (PMID 37031183, 2023). "IRAK1 knockdown inhibits malignancy and enhances the radiosensitivity of glioma in vitro and in vivo." (PMID 37031183, 2023). "Our findings uncovered that IRAK1 knockdown promotes G2/M phase arrest, apoptosis, especially with IR treatment, and radiosensitization of glioma cells." (PMID 37031183, 2023). "In the present study, we revealed that radiation remarkably induces IRAK1 expression and IRAK1 inhibition sensitizes glioma cells to radiation both in vitro and in vivo." (PMID 37031183, 2023). "As radiation is a principal adjuvant therapy for treating glioma, we next measured the protein expression of IRAK1 in cells that received different doses of X-ray irradiation (IR)." (PMID 37031183, 2023). "Since the miRNA data of GBM patients were not available in TCGA database, we analyzed the correlation of miR-146a-5p vs. TRAF6 and vs. IRAK1 in the Chinese Glioma Genome Atlas (CGGA) database." (PMID 37391426, 2023). "The results showed that glioma patients with high IRAK1 expression had higher RSI, indicating more resistance to radiation therapy." (PMID 37031183, 2023). "For glioma patients who received radiotherapy, the IRAK1 low expression group exhibited an obvious survival advantage compared with IRAK1 high expression ones." (PMID 37031183, 2023). "Taken together, these results suggested that IRAK1 promotes the radioresistance of glioma cells by PRDX1-mediated suppression of autophagic cell death." (PMID 37031183, 2023). "We next performed clonogenic survival assays to further investigate the effect of IRAK1 after DNA damage in glioma cells." (PMID 37031183, 2023). "The correlation between TRAF6 and IRAK1 was evaluated with immunofluorescence (IF)-stained clinical glioma samples." (PMID 37391426, 2023). "The reduced phosphorylation levels of Akt and mTOR in IRAK1 depletion glioma cells were restored by PRDX1 overexpression, ATG5 knockdown or 3-MA treatment." (PMID 37031183, 2023). "The functions of a series of E3 ubiquitin ligases have been reported in glioma, for instance, radiation induces E3 ligase IRAK1 expression to promote radioresistance of glioma by decreasing the ubiquitination of PRDX1 and suppressing autophagy." (PMID 37723588, 2023). "Cell cycle distribution analysis showed that the combination of IR and IRAK1 knockdown significantly induced the G2/M arrest of glioma cells." (PMID 37031183, 2023). "Similar to the observation in the glioma cohort from our department, IRAK1 mRNA expression was higher in glioma, including LGG and GBM, as compared to nontumor tissues in TCGA and Rembrandt databases." (PMID 37031183, 2023). "To investigate the role of IRAK1 played in glioma, we first assessed its expression levels in glioma and benign brain tumor tissues by IHC analysis." (PMID 37031183, 2023). "IRAK1 expression was much upregulated in glioma tissues in comparison with benign brain tumor tissues." (PMID 37031183, 2023). "The results of CCK-8 assays showed that the proliferation rate was significantly diminished in sh-IRAK1 glioma cells compared to the control cells." (PMID 35211171, 2022). "Firstly, Hs683 and SW1088 glioma cell lines were transfected with IRAK1 knockdown lentivirus, which was verified using Western blot analysis." (PMID 35211171, 2022).
glioma (continued). "Additionally, a study on glioma cells reported similar findings where IRAK1 knockdown led to the reduction in MMP-2 protein levels." (PMID 39451208, 2024). "We found that silencing IRAK1 inhibited the malignant transformation of glioma cells in vitro." (PMID 38830885, 2024). "Additionally, studies on glioma cells reported similar findings where IRAK1 knockdown led to the reduction in migration and invasion, alongside an increase in E-cadherin expression and a decrease in N-cadherin and vimentin levels." (PMID 39451208, 2024). "We further explored the biological functions of IRAK1 in gliomas." (PMID 38830885, 2024). "Moreover, we determined the effects of HNRNPC on the proliferation, migration, and invasion of glioma cells via IRAK1 using rescue experiments." (PMID 38830885, 2024). "Furthermore, our results demonstrated that HNRNPC positively regulated IRAK1 levels in glioma cells." (PMID 38830885, 2024). "To investigate whether IRAK1 is responsible for HNRNPC function during glioma tumorigenesis, we knocked down IRAK1 in a background of ectopic HNRNPC expression." (PMID 38830885, 2024). "Furthermore, in agreement with the TCGA and CGGA data, our IHC TMA results revealed that patients with glioma and high IRAK1 expression had a worse OS than those with low IRAK1 expression." (PMID 38830885, 2024). "We found that glioma patients with overexpressed IRAK1 show a poor prognosis." (PMID 37031183, 2023). "Herein, our investigation also confirmed that IRAK1 knockdown sensitizes glioma cells to radiation." (PMID 37031183, 2023). "The protein levels of TRAF6 and IRAK1 were estimated with IF-stained glioma samples." (PMID 37391426, 2023). "Meanwhile, transwell assays revealed that IRAK1 silencing could remarkably impede the migratory and invasive ability of glioma cells." (PMID 37031183, 2023). "Moreover, the Spearman correlation analysis between IRAK1 expression pattern and clinical characteristics of glioma patients was conducted." (PMID 37031183, 2023). "Additionally, IRAK1 inhibition increased the apoptosis rates of irradiated glioma cells detected by flow cytometry." (PMID 37031183, 2023). "IRAK1 expression and its correlation with prognosis were analyzed in glioma tissues." (PMID 37031183, 2023). "Meanwhile, glioma patients with higher expression of IRAK1 exhibited a shorter overall survival." (PMID 37031183, 2023). "Furthermore, IRAK1 knockdown in glioma cells significantly induced the percentage of DNA tail in response to IR treatment at both 30 min and 24 h time points, indicating there exist delays in DNA damage repair in the IRAK1-deficient cells." (PMID 37031183, 2023). "However, very little is known about the effects of IRAK1 on tumor radioresistance and malignant behaviors in glioma." (PMID 37031183, 2023). "Together, all these results suggested that the radioresistance of glioma cells is impaired by IRAK1 knockdown, which could be reversed by overexpression of PRDX1." (PMID 37031183, 2023). "In summary, the results of our research suggest that IRAK1 could be a potential novel biomarker and radiotherapy desensitizer in glioma." (PMID 37031183, 2023). "To determine whether IRAK1 depletion promotes the radiosensitivity of glioma cells in vivo, we generated U251-derived xenograft nude mice models." (PMID 37031183, 2023). "We, therefore, built IRAK1-knockdown glioma cell models based on U251 and A172 cells." (PMID 37031183, 2023). "Our results showed that the facilitation of IRAK1 on glioma cell migration and invasion could be partially explained by the upregulated expression of E-cadherin and the downregulated expression of N-cadherin and Vimentin." (PMID 37031183, 2023). "Moreover, glioma patients with higher IRAK1 expression exhibited a shorter survival time." (PMID 37031183, 2023).